AR (androgen receptor)
Diseases named in the same sentence as AR in open-access papers (continued):
Sharing a sentence is not in itself a finding about the gene and the disease.
breast carcinoma (continued). "AR agonism has suppressed the growth of HR+ endocrine-sensitive and -resistant breast cancers in preclinical models." (PMID 36980743, 2023). "In this study, we systematically analyzed the relationship between the expression of sex steroid hormone receptors such as ER, PgR, and AR and the immunological profiles of breast cancer tissues." (PMID 36721218, 2023). "Since AR also has roles in other cancer entities, mostly in prostate and in breast cancer, multiple inhibitors and antagonists of AR have been developed and trialed, yielding successful therapeutic targeting of the AR in these cancer entities." (PMID 36906590, 2023). "It is widely expressed in all breast cancer subtypes to varying extents, with approximately 60–80% of the cases being AR-positive." (PMID 36721218, 2023). "The activation of the AR plays a central role in regulating breast cancer progression, although its specific function in TNBC is still under debate." (PMID 37681860, 2023). "We aim to better understand how AR is expressed in breast cancer that has spread to the brain, i.e., brain metastases (BrM)." (PMID 37345085, 2023). "The Androgen Receptor (AR) is emerging as an important factor in the pathogenesis of breast cancer (BC) and represents the latest addition to the worldwide IHC panel." (PMID 37189515, 2023). "The aim of present study was to investigate AR expression in relation to clinicopathological features, molecular subtypes, pCR rate and prognosis in primary breast cancer treated with neoadjuvant chemotherapy." (PMID 37099044, 2023). "Hormone dependence of MCF7 cells is supported mainly through the ERα signaling pathway, and AR expression is also detected in these cells—this steroid hormone receptor is considered as a new target in breast cancer cells." (PMID 38256865, 2023). "AR positive expression was an independent protective factor for the outcome of HR + /HER2-, HR + /HER2 + breast cancer, and an independent risk factor for TNBC." (PMID 37099044, 2023). "We aimed to evaluate the expression of the “targetable” androgen receptor (AR) in breast cancer brain metastases (BrM)." (PMID 37345085, 2023). "A study that reviewed 980 consecutive cases of invasive breast carcinomas found that AR was notably expressed in ER− breast cancer and TNBC." (PMID 37237509, 2023). "It is known that AR is expressed in 85–95% of ER+ breast cancer cases and in 77% of invasive breast cancers." (PMID 36677847, 2023). "AR expression is prevalent in breast cancer subtypes and has been found to be about 50% expressed in ER breast cancer types." (PMID 38137912, 2023). "Gene analysis in this study indicated that in HER2-enriched breast cancers, OS with AR mRNA expression was significantly better." (PMID 37085500, 2023). "Then, there were also variations between the AR– and AR + breast cancer in different subtypes, grouped by molecular subtype." (PMID 36929229, 2023). "SDC1 and the AR have been identified as molecular markers with a high expression in breast cancer tissues compared to normal tissues." (PMID 36980680, 2023). "Many studies have found that activated AR inhibits cancer cell proliferation in most ER+ breast cancers and promotes cancer cell growth in most ER− breast cancers." (PMID 37237509, 2023). "[18F]FDHT PET can be used for assessing AR expression in breast cancer and 18F-fluoroestradiol ([18F]FES) PET for visualizing ER expression in tumor lesions." (PMID 37175938, 2023). "On ultrasound, 98.59% (70/71) of AR + breast cancer showed unsmooth margin on ultrasound; however, that of AR– was 72.73% (24/33)." (PMID 36929229, 2023).
breast carcinoma (continued). "AR expression in breast cancer BrM is of interest due to readily available androgen-targeted therapies that can cross the blood brain barrier." (PMID 37345085, 2023). "The ER− or PR− status in breast cancer cell lines can determine if AR-targeted hormone therapy would be beneficial." (PMID 38137912, 2023). "Taken together, these studies indicate that AR is important in each molecular subtype of breast cancer, and therefore, further exploration is urgently needed." (PMID 36929229, 2023). "MDA-MB-453 breast cancer cell line, in particular, has a high level of AR, which has been shown to play a vital role in breast cancer pathogenesis." (PMID 38137912, 2023). "Our study showed that HER2+ breast cancer BrM most frequently express AR, and suggests that there is a need to elucidate the biology of AR in HER2+ breast cancer." (PMID 37345085, 2023). "The androgen receptor (AR) plays a critical role in normal breast physiology and breast cancer pathology." (PMID 38203649, 2023). "The frequency of AR expression differs between breast cancer subtypes, varying from 85–95% in ER-positive (ER+) to 15–75% in ER-negative (ER−) breast tumors." (PMID 37686282, 2023). "In breast cancer tumors with ER expression, AR and ER regulate each other’s transcription, and the ratio between the two receptors determines the outcome." (PMID 38067367, 2023). "Some studies have also indicated that AR is correlated with endocrine therapy resistance in breast cancer." (PMID 37237509, 2023). "Prostate and breast cancers often depend on hormone receptors: an androgen receptor (AR) and an estrogen receptor (ER), respectively." (PMID 37296881, 2023). "This is supported by gene expression of critical genes in breast cancer pathology, such as AR, the androgen receptor gene." (PMID 36598637, 2023). "Similar patterns of BAD cellular levels and localization were also observed in ER+/AR+ T47D and ZR75, as well as in ER−/AR+ SKBR3 breast cancer cells." (PMID 37686282, 2023). "Androgen receptor (AR) expression in estrogen receptor-positive (ER+) breast cancer (BC) correlates with lower tumor grade and a better clinical outcome." (PMID 37686282, 2023). "In 10 patients for whom matched BrM and primary breast cancers were available, AR expression by IHC was higher in primary breast cancers compared to matched BrM (79% vs. 52%, Wilcoxon signed rank test p < 0.05)." (PMID 37345085, 2023). "This study used a clinically validated antibody (SP107) to show in a 57-patient retrospective Canadian cohort that the majority of breast cancer BrM were AR positive (defined as AR ≥ 10% by IHC)." (PMID 37345085, 2023). "AR was detected in 373 (86.9%) of 429 HR + /HER2 + breast cancers, and in 127 (72.2%) of 176 cases of HR-/HER2 + breast cancers." (PMID 37099044, 2023). "MDA-MB-453 cells are an androgen-responsive breast carcinoma cell line with high-level AR expression." (PMID 38137912, 2023). "In HR + /HER2 + breast cancer patients, 91 (24.4%) of 373 AR positive achieved pCR, and the pCR rate was 26.8% (15/56) in AR negative patients (P = 0.769)." (PMID 37099044, 2023). "Androgen receptor (AR) is a receptor found on many breast cancer cells, and drugs can be used to target AR in the treatment of advanced breast cancers." (PMID 37345085, 2023). "SARMs also have been used for treating triple-negative breast cancer cells, where they suppress the expression of genes and their associated pathways intratumorally, which encourages the development of breast cancer via its actions on the AR." (PMID 36891053, 2023). "One of the most commonly overexpressed steroid nuclear receptors in breast cancer patients is the androgen receptor (AR), with a 70% occurrence leading to increased pathogenesis." (PMID 37835396, 2023). "A preclinical treatment study using the antiandrogen enzalutamide demonstrated growth inhibition of AR-positive breast cancer including in a TNBC model." (PMID 37583424, 2023).
breast carcinoma (continued). "Corresponding cell line studies showed that AR + luminal subtype breast cancer cells are resistant to chemotherapy and more likely to benefit from AR antagonists." (PMID 37662839, 2023). "High levels of PR, ER, and AR expression are well-established markers for a favorable prognosis of breast cancer patients." (PMID 38137396, 2023). "In conclusion, AR is closely related to the clinicopathological features and prognosis of breast cancer." (PMID 36929229, 2023). "In this study, we have comprehensively analyzed the relationship between the expressions of estrogen (ER), progesterone (PgR), and androgen receptors (AR), and the immunological profile in breast cancer." (PMID 36721218, 2023). "Many of these breast cancer cell lines are categorized by the hormonal receptors ER, PR, and AR that are derived from the breast cancer patient of origin." (PMID 38137912, 2023). "We found that AR was expressed in the majority of BrM, and was expressed at different frequencies across different types of breast cancer." (PMID 37345085, 2023). "The activation of AR represses ER-regulated cell cycle genes and upregulates AR target genes which include tumour suppressors, and this supports the rationale for ongoing trials evaluating AR agonists in ER+ breast cancer." (PMID 37345085, 2023). "In this study, we report a novel, additional, mechanism that contributes to explain the protective, anti-proliferative role exerted by androgens/AR signaling in ER+ breast cancers." (PMID 37686282, 2023). "The fact that our study shows a high proportion of breast cancer BrM are AR-positive using a biomarker predictive of response to anti-androgen therapies, supports the evaluation of AR-targeted therapies in breast cancer patients BrM." (PMID 37345085, 2023). "As demonstrated in several prostate and breast cancer cell lines for their AR-/ER-specificity and different levels of pro-/anti-inflammatory cytokines, these results can preciously depict the phenotypic features of the cell lines." (PMID 37669926, 2023). "AR is expressed in 70–90% of breast cancer cases, but its function seems to vary among different breast cancer subtypes." (PMID 37189515, 2023). "With respect to AR expression by IHC in primary breast cancers, our results are comparable to those of other studies, which consistently report that AR is expressed in 72–79% of primary breast cancers." (PMID 37345085, 2023). "For example, SARM RAD140 substantially inhibits the growth of AR/ER+ breast cancer patient-derived xenografts (PDX) by activating the AR and by suppressing ER-α action." (PMID 36891053, 2023). "AR expression was different across breast cancer subtypes; AR was most frequently expressed in HER2+ (n = 21/28), followed by HR+/HER2− (n = 9/17), and lowest in TNBC (n = 2/12) BrM (p = 0.003)." (PMID 37345085, 2023). "Previous studies showed that most luminal breast cancers expressed AR, and this expression suggested a good prognosis." (PMID 37099044, 2023). "The AR is expressed in about 60% of early breast cancer cases, with a higher prevalence in ER-positive tumors compared to ER-negative tumors." (PMID 37681860, 2023). "Patients with AR+ BrM had a numerically longer median time from diagnosis of breast cancer to diagnosis of BrM, compared to those with AR− BrM, although this was not statistically significant (51 vs. 29 months, p = 0.16)." (PMID 37345085, 2023). "Our research demonstrated that AR expression was closely related to ultrasound, clinicopathological features and prognosis of breast cancer." (PMID 36929229, 2023). "Many of the associations that we found between the expression of AR and the expression of other prognostic and proliferation markers (GATA3 and Ki-67) are in keeping with what is known about the biology of breast carcinomas." (PMID 37345085, 2023). "Additional studies are needed to improve our understanding of AR and its role in breast cancer development and prevention." (PMID 37583424, 2023).
breast carcinoma (continued). "In ER (−), HER 2 (+) breast cancer, AR transcriptional activity is promoted which increases tumor growth." (PMID 38067367, 2023). "About 60 to 80% of breast cancer patients express androgen receptor (AR) and approximately 90% of ER-positive breast cancer patients express AR." (PMID 37900137, 2023). "Altogether, we studied the correlation between AR status and ultrasound, clinicopathological features and clinical outcomes in breast cancer, although our research still has some limitations." (PMID 36929229, 2023). "The authors emphasize that these results show the potential use of AR and ER imaging for receptor status assessment, particularly in respect to biopsy sampling errors and heterogeneous AR and/or ER expression in breast cancer metastases." (PMID 37175938, 2023). "We first analyzed the AR expression in different subtypes of breast cancer and its correlation with clinicopathological features." (PMID 37099044, 2023). "Because our results and previous studies demonstrate that AR expression has prognostic value, it is recommended that AR status should be evaluated for patients with HER2-enriched breast cancer upon initial diagnosis to obtain comprehensive information." (PMID 37085500, 2023). "As a new molecular marker of breast cancer and an important prognostic factor, AR will play an increasingly important role in diagnosing and treating breast cancer." (PMID 36929229, 2023). "Further investigation is warranted to elucidate breast cancer risks in transgender individuals receiving exogenous testosterone of varying durations and its roles in altering ER and AR." (PMID 37951051, 2023). "AR is emerging as a new biomarker and potential therapeutic target in the treatment of breast cancer patients." (PMID 37099044, 2023). "Several studies have confirmed that AR can be used as a potential therapeutic target and an emerging prognostic marker to guide the clinical treatment of breast cancer." (PMID 36929229, 2023). "In a previous study of 55 patients with HER2-positive breast cancer who received trastuzumab plus pertuzumab neoadjuvant therapy, pCR positively related to high expression levels of AR (OR 33.145, 95% CI 2.803 to 391.900, P = 0.005)." (PMID 37099044, 2023). "Another regulating mechanism of the PIP gene was found in a subtype of ER-negative, AR-positive breast cancer called molecular apocrine." (PMID 37759471, 2023). "In this line, androgen receptor (AR), which is a nuclear hormone receptor, has been identified as a potential therapeutic target in breast cancer, particularly in the luminal androgen receptor (LAR) subtype of TNBC." (PMID 37176102, 2023). "Steroid receptors including ER, PR, glucocorticoid receptor (GR), and androgen receptor (AR) have been shown to play an important role in breast cancer progression." (PMID 36347335, 2023). "There were 418 cases of HR + /HER2- breast cancer, of which 345 cases were AR positive, and the AR positive rate was 82.5%." (PMID 37099044, 2023). "In conclusion, this study systematically investigated the association of AR expression with pCR after neoadjuvant therapy and DFS in different subtypes of breast cancer." (PMID 37099044, 2023). "This raises the question to investigators: what is the connection between AR and ERα signaling in breast cancer?" (PMID 35053220, 2022). "AR’s high ratio of expression (78%) provides an optimal sensitive and specific index to predict the prognosis of breast cancer, and the ratio of AR : ERα over 0.87 suggests the best outcome in ERα-positive breast cancer (p < 0.0001)." (PMID 35800434, 2022). "Worthy of note, FOXA1 is an interacting partner of both the estrogen and androgen receptor, playing a crucial role in the development and progression of breast cancer." (PMID 36230619, 2022). "In ERα-positive breast cancers, androgens suppress estrogen-dependent growth, partially due to the suppressive effects of androgens/AR on ERα transactivation." (PMID 37435447, 2022).
breast carcinoma (continued). "We confirmed that BQ overexpression enhanced the expression of IL-8 in ER+ve breast cancer cells, and AR inhibition reduced IL-8 expression in the BQ overexpressing cell lines, suggesting that AR was involved in the modulation of IL-8 expression by BQ." (PMID 35054486, 2022). "Our result show that ER−/AR+ breast cancer shares similar characteristics with LAR in terms of low proliferation index and older age at diagnosis." (PMID 36232774, 2022). "Second, our analysis only focused on the HER2-negative breast cancer, and previous studies demonstrated that the correlation between AR pathway activity and AR expression varied in HER2-positive and HER2-negative breast cancer." (PMID 36232774, 2022). "In our study, the proportion of breast cancers with AR expression was 86%, which matched the literature." (PMID 35207749, 2022). "Therein, this narrative review will discuss the potential for targeting the AR in breast cancer treatment." (PMID 36499670, 2022). "This study identified 12% (n = 51) of tumours were AR-expressing breast tumours among 424 patients with ER/PR-negative breast cancer." (PMID 35877237, 2022). "A study that determined AR’s clinical significance in luminal-B breast cancers showed that the AR + ve cases would have better outcomes for time-to-relapse (TTR) and disease-specific survival (DSS)." (PMID 35053220, 2022). "While AR is expressed in the majority of breast cancers (70–90%), expression is less prevalent in TNBC (10–50%)." (PMID 35203574, 2022). "The androgen receptor (AR) is widespread across various breast cancer subtypes, and over 70% of HR–positive breast cancers express AR." (PMID 36556209, 2022). "The androgen receptor (AR) is a biomarker that is widely expressed in all breast cancer subtypes and is probably related to treatment response and prognosis." (PMID 35207749, 2022). "These actions contribute to the continuous development of the tumor, leading to poor survival of the patients, rendering the AR a poor prognostic factor in ERα-ve breast cancer." (PMID 36499670, 2022). "Next, clonogenic survival assays were performed with 25–250 nM ARD-61 in AR+/ER+ breast cancer cells." (PMID 35618789, 2022). "Selective androgen receptor modulators (SARMs) are clinically available and are being investigated as medicine for AR-positive breast cancer." (PMID 36232774, 2022). "The representative compound, PROTAC 12, potently degraded AR in AR + breast cancer cell lines and was much more potent than enzalutamide in inhibition of cell growth and induction of cell cycle arrest and/or apoptosis." (PMID 35702041, 2022). "AR is expressed in approximately 90% of ER+ breast cancers and its expression is related to a favorable prognosis by antagonizing ER." (PMID 36584207, 2022). "Together these findings suggest a role for nuclear hormone receptors in the radiation response and warrant further investigation of AR and ER inhibition in AR+/ER+ breast cancer models." (PMID 35618789, 2022). "Conversely, in TNBC breast cancers, a significant positive correlation between AR and CD3-positive T cell infiltration was observed." (PMID 37435447, 2022). "From the keyword analysis, AR gene expression in different molecular types of breast cancer was the main emphasis of the research area at the beginning and then the mechanism and signal pathway of the action of ARs took over a partial position." (PMID 35800434, 2022). "TNBC is higher in Africans (23%–82%) and African-Americans (29.8%) compared to Caucasian (10%–15%) breast cancer patients; however, there is a paucity of data on AR expression in this population." (PMID 36405944, 2022). "Regarding “androgen receptor expression”, we need to identify the meaningful AR threshold in breast cancer before discussing the significance of ARs." (PMID 35800434, 2022). "Enzalutamide is the most widely used AR inhibitor and is currently being explored in multiple clinical trials in breast cancers (NCT04142060, NCT03207529, NCT02689427)." (PMID 35618789, 2022).